GSDMD (gasdermin D)
Diseases named in the same sentence as GSDMD in open-access papers (continued):
Sharing a sentence is not in itself a finding about the gene and the disease.
ovarian carcinoma (17 papers, 2021 to 2025). A malignant neoplasm originating from the surface ovarian epithelium. "What is more, a later published paper further convinced that α-NETA treatment causes epithelial ovarian cancer cell death through pyroptosis, with a dramatically augmented level of GSDMD, caspase-4, LC3B, and IL-18 secretion." (PMID 35198448, 2022). "We recently demonstrated that polyunsaturated fatty acids trigger a caspase-1/GSDMD-mediated pyroptosis in ovarian cancer cells in a mechanism requiring translational augmentation of caspase-1 that is independent of ASC/inflammasome." (PMID 40701951, 2025). "Further mechanistic analysis indicated that CA induces pyroptosis in ovarian cancer through the CASP4/TXNIP-NLRP3-Gasdermin-D (GSDMD) pathway, thereby inhibiting ovarian cancer cell growth and presenting a potential therapeutic approach." (PMID 40718836, 2025). "A new drug known as 2‐(anaphthoyl)ethyltrimethylammonium iodide (α‐NETA), a choline acetyltransferase inhibitor, hinders the development of epithelial ovarian cancer by activating pyroptosis via the GSDMD/caspase 4 pathway." (PMID 37752941, 2023). "α‐NETA exhibits much lower cytotoxic effect after the knockdown of either caspase‐4 or GSDMD in ovarian cancer cells and decreases the growth of epithelial ovarian tumor in vivo." (PMID 37125240, 2023). "The cytotoxic effect of a-NETA was strongly blocked by knockdown of either GSDMD or caspase-4 in ovarian cancer cells." (PMID 35673561, 2022). "Nobilin reduces mitochondrial membrane potential and induces the generation of reactive oxygen species and autophagy of human ovarian cancer cells (HOCCs), leading to GSDMD/GSDME-mediated pyroptosis." (PMID 35883480, 2022). "However, α-NETA or citric acid was found to inhibit epithelial ovarian cancer cell growth by inducing caspase-4/GSDMD-mediated pyroptosis." (PMID 40701951, 2025). "In their TMEs, ovarian cancer patients have greater GSDMD and lower GSDME protein levels." (PMID 37752941, 2023). "However, exceptions exist, as autophagic inhibition in ovarian cancer cells hindered pyroptosis by downregulating active GSDMD and GSDME." (PMID 38007535, 2023). "The pyroptosis of epithelial ovarian cancer cells could be triggered by 2‐(anaphthoyl) ethyl‐trimethylammonium iodide (α‐NETA) through pathway of caspase‐4/GSDMD." (PMID 37125240, 2023). "So the role of GSDMD may be also an interesting target by DSF in ovarian cancer." (PMID 37305383, 2023). "The expression of GSDMD and GZMB were both significantly correlated with Pyrsig score (P = 0.018 and P = 0.034, respectively) in 65 ovarian cancer patients." (PMID 36707884, 2023). "In the genes that code for GSDMC, GSDMD, GSDME, and PJVK, ovarian cancer has the highest rate of copy number variation events of any cancer type." (PMID 37752941, 2023). "Regarding the influence of pyroptosis on autophagy, necrosulfonamide (NSA) treatment, a specific GSDMD inhibitor, resulted in diminished LC3II expression in ovarian cancer cells." (PMID 38007535, 2023). "NOB, a polymethoxyflavonoid, stimulates traditional autophagy, ROS production, and a decline in MMP, all of which contribute to initiating GSDMD/GSDME‐mediated pyroptosis and upregulating the expression of IL‐1β and ASC in ovarian cancer." (PMID 37752941, 2023). "However, some PYAGs with CNV gain, such as GSDMD, TP63, PRKACA, PJVK and CASP4, showed downregulated mRNA expression in ovarian cancers, and some PYAGs with CNV loss, such as IL18, GPX4, GZMA, NLRP6 and CASP6, showed upregulated mRNA expression in ovarian cancers." (PMID 36707884, 2023). "In the gasdermin family, GSDMA (logFC=1.38557, FDR=5.23e-15) and GSDMC (LogFC=2.298323, FDR=2.06e-38) was significantly overexpressed in ovarian cancer, while the expression of GSDMD (logFC=-1.10275, FDR=8.25e-30) and GSDME (logFC=-2.29572, FDR=1.54e- 46) was significantly lower in ovarian cancer." (PMID 37859811, 2023).
ovarian carcinoma (continued). "GSDMD has also been investigated as a potential therapeutic target in cancer: treating endometrial or ovarian cancer cells with α-NETA, a reversible choline acetylcholine transferase inhibitor, induced pyroptosis via the GSDMD/caspase-4 pathway, and reduced tumor growth in mice." (PMID 35844522, 2022). "At present, studies have shown that GSDMD 7, 33 and GSDME 32, 33 are the key targets that cause pyroptosis in ovarian cancer cells, while GSDMA and GSDMC have not been proven to be involved in the pyroptosis of ovarian cancer cells, which is consistent with our analysis results." (PMID 37859811, 2023).
systemic lupus erythematosus (17 papers, 2020 to 2025). An autoimmune multi-organ disease typically associated with vasculopathy and autoantibody production. "Such notion was also supported by transcriptome sequencing data from lupus models, which showed myeloid GSDMD-deficiency drove an upregulation of mitotic cell division genes and downregulation of cytosolic calcium concentration genes." (PMID 38831451, 2024). "Functionally, GSDMD deficiency led to increased pathogenic neutrophil extracellular traps (NETs) in lupus peripheral blood and bone marrow-derived neutrophils." (PMID 38831451, 2024). "A competitive reconstitution assay is needed to better describe the cell intrinsic effect of GSDMD, and myeloid progenitors-conditional deficient mice are of higher value to study lupus-related granulopoiesis in future studies." (PMID 38831451, 2024). "GSDMD deletion and myeloid-intrinsic GSDMD deficiency in lupus mice significantly exacerbated systemic autoimmune and renal damages, with abnormal granulopoiesis manifested by elevated immature neutrophils and granulocyte/macrophage progenitors (GMPs)." (PMID 38831451, 2024). "Using the pristane-induced lupus model, we show that disease severity is significantly reduced in mice with neutrophil-specific Gsdmd deficiency or following treatment with the GSDMD inhibitor, disulfiram." (PMID 36797275, 2023). "In conclusion, our study revealed that myeloid-intrinsic GSDMD deficiency could drive granulopoiesis by reducing calcium influx in myeloid progenitor cells, and promote neutrophil-mediated renal injury in lupus milieu." (PMID 38831451, 2024). "For example, GSDMD deficiency in Lupus enhances systemic autoimmunity." (PMID 36967609, 2023). "In contrast, GSDMD knockout ameliorated severe symptoms such as splenomegaly, proliferative glomerulonephritis, and interferon‐alpha signaling in the pristane‐induced lupus (PIL) murine model." (PMID 38881675, 2024). "Global or myeloid-conditional deletion of GSDMD was shown to exacerbate systemic autoimmunity and renal injury in lupus mice with both chronic graft-versus-host (cGVH) disease and nephrotoxic serum (NTS) nephritis." (PMID 38831451, 2024). "We found that the LPS translocated from the gut was able to trigger Caspase 11/GSDMD induced pyroptosis of macrophages in lupus‐prone mice." (PMID 38881675, 2024). "Following cGVH induction, GSDMD deletion exhibited more severe lupus-like systemic autoimmune disorders than wild-type controls, with markedly increased serum autoantibodies against dsDNA, ssDNA and histones, as well as enhanced splenomegaly." (PMID 38831451, 2024). "Our findings provide new evidence and insights into a comprehensive understanding of the paradoxical functions of GSDMD in lupus, which is indeed important for the rationale of implementing GSDMD interventions in LN." (PMID 38831451, 2024). "We enrolled three healthy individuals and four patients with varying Systemic Lupus Erythematosus Disease Activity Index (SLEDAI) to assess GSDMD cleavage in PBMCs." (PMID 38881675, 2024). "Next, we validated the same GSDMD expression pattern in three widely used lupus models, including spontaneous lupus mouse NZB/W F1, bm12 splenocyte-induced cGVH model and NTS nephritis." (PMID 38831451, 2024). "GSDMD was proteolytically activated in the neutrophils of SLE patients as well as in pristane-induced and MRL/lpr mouse models of lupus, and GSDMD-mediated pyroptotic death of neutrophils was increased in the kidneys of these lupus mouse models." (PMID 38396768, 2024). "GSDMD mRNA levels in neutrophils of LN patients were significantly negatively correlated with disease activity as reflected by Systemic Lupus Erythematosus Disease Activity Index (SLEDAI) score." (PMID 38831451, 2024). "We observed increased Caspase 5/11 and GSDMD‐dependent pyroptosis in the macrophages/monocytes of both lupus patients and mice." (PMID 38881675, 2024).
systemic lupus erythematosus (continued). "Surprisingly, GSDMD knockout mice developed more severe lupus symptoms, including higher spleen/body weight ratios, increased proteinuria, and extensive renal and lung damage, alongside elevated mortality rates compared with imiquimod‐treated wild‐type mice." (PMID 38881675, 2024). "These insights shed light on the intricate and multifaceted role of GSDMD in modulating myeloid cell differentiation through ion fluxes, thereby offering novel perspectives on the role of GSDMD in the immunopathology of lupus." (PMID 38831451, 2024). "In this study, we confirmed the enhanced Caspase 5/11‐induced GSDMD activation in macrophages of lupus patients and lupus‐prone MRL/lpr mice." (PMID 38881675, 2024). "To further explore how GSDMD modulates myeloid cells to protect against lupus, we performed whole-transcriptome sequencing (RNA-seq) analysis using CD11b+ cells sorted from the spleens of Gsdmdfl/fl and Gsdmd△Lyz2 cGVH mice, respectively." (PMID 38831451, 2024). "At the protein level, there was an increase in the cleavages of Caspase 11 and GSDMD in the kidneys of lupus mice compared with healthy control (C57BL/6 mice)." (PMID 38881675, 2024). "Extensive neutrophil extracellular DNA release (as detected by Sytox Green staining) was observed following lupus serum (LS) treatment, and this release was suppressed upon treatment with the GSDMD inhibitor, disulfiram (DSF)." (PMID 36797275, 2023). "We then focused on GSDMD, which was significantly upregulated together with caspase-1 and caspase-4 (also known as caspase-11 in mice) upregulation in lupus mice." (PMID 36797275, 2023). "The content of GSDMD increased significantly in the lungs of PH mice systemic lupus erythematosus (SLE) along with PH." (PMID 36841823, 2023). "Increased glomerular neutrophil infiltration was also detected in two murine lupus models, wherein the infiltrated neutrophils showed increased GSDMD expression as compared to the control." (PMID 36797275, 2023). "Of note, DSF weakened the intensity of immunofluorescent staining of GSDMD in the glomerular macrophages of lupus mice." (PMID 36057687, 2022). "Moreover, ox-mtDNA and GSDMD interact directly in neutrophils from patients with systemic lupus erythematosus, thereby promoting GSDMD-NT oligomerization, pore formation, and cell death." (PMID 40243714, 2025). "While GSDMD has been studied previously in systemic lupus erythematosus (SLE), the role of pyroptosis in SLE pathogenesis remains unclear and contentious, with limited understanding of Caspase 11‐mediated pyroptosis in this condition." (PMID 38881675, 2024). "In addition, the caspase-11 non-canonical inflammasome is activated in the neutrophils of lupus mice, leading to the proteolytic activation of GSDMD and extracellular DNA release through GSDMD pores." (PMID 38396768, 2024). "Paradoxically, recent follow-on studies found that neutrophils-specific GSDMD deficiency or administration of the GSDMD inhibitor disulfiram/Ac-FLTD-CMK alleviated disease severity in pristane-induced lupus model, in which the assembly of GSDMD pores promoted NETs formation." (PMID 38831451, 2024). "The role of GSDMD in murine lupus models remains highly controversial." (PMID 38831451, 2024). "Interestingly, oxidized mtDNA promotes GSDMD oligomerization and pore formation, resulting in the pyroptotic death of neutrophils in mouse models of lupus." (PMID 38396768, 2024). "There are signs of elevated GSDMD‐mediating pyroptosis exists both in patients and mice with lupus." (PMID 38881675, 2024). "Furthermore, inhibiting Caspase 11 and repairing the gut barrier with antibiotics effectively suppressed the Caspase 11/GSDMD pathways, thereby alleviating the manifestations of lupus in mice." (PMID 38881675, 2024). "highlighted a potential protective role of GSDMD in imiquimod (a TLR7 agonist)‐induced lupus model." (PMID 38881675, 2024).
systemic lupus erythematosus (continued). "Furthermore, pristine-induced Sytox Green positive staining neutrophils in renal sections reduced significantly in Gsdmd−/− lupus mice, thus indicating GSDMD-dependent cell death in lupus mice." (PMID 36797275, 2023). "Collectively, these results suggested that GSDMD was significantly activated in neutrophils from both lupus mice and SLE patients and may contribute to the generation of NETs and mtDNA release." (PMID 36797275, 2023). "Both caspase-1 and −11 are required for GSDMD activation upon exposure to lupus serum." (PMID 36797275, 2023). "Our study discovered that GSDMD is a key regulator of granulopoiesis by combining unbiased RNA-sequencing data and a series of validation experiments, which may fill the gap in the regulation of granulopoiesis in lupus." (PMID 38831451, 2024). "Furthermore, GSDMD inhibition in neutrophils alleviates disease severity in mouse models of lupus." (PMID 38396768, 2024). "However, whether these molecules are involved in GSDMD-regulated granulopoiesis is unknown and worth exploring in the future, especially considering the important roles of inflammasomes in lupus progress." (PMID 38831451, 2024). "In these two models, by utilizing global- and myeloid-conditioned GSDMD-knockout mice, we proved the protective effect of GSDMD in the pathogenesis of LN and proposed that GSDMD was a key mediator of neutrophil homeostasis under lupus conditions, with the potential to stimulate granulopoiesis." (PMID 38831451, 2024). "However, the mechanisms that regulate the cleavage of GSDMD in neutrophils of lupus mice remain unknown." (PMID 36797275, 2023). "P2X7 stimulation likely controls the development of pathogenic ICOS+ IFN-γ-secreting Tfh cells, which characterize systemic lupus erythematosus (SLE), by inducing pyroptosis via caspase-mediated activation of gasdermin D." (PMID 32587592, 2020). "Recent data suggested that ox-mtDNA interacts with GSDMD and stabilizes its oligomerization in neutrophils, generating a vicious cycle that further promotes extracellular mtDNA in systemic lupus erythematosus (SLE)." (PMID 40264103, 2025). "Lupus-related damage-associated molecular patterns (DAMPs) may increase GSDMD’s expression through inflammasomes, yet there is no clear evidence linking it to increased pyroptosis in lupus, hinting at possible non-lytic roles of GSDMD in such conditions." (PMID 38831451, 2024). "Adding to the confusion, GSDMD-global knockout has previously been shown to increase myeloid cell expansion and accelerate lupus phenotypes in TLR7 agonist- or pristane-induced lupus models, which actually coincide with our phenotypic conclusions." (PMID 38831451, 2024). "This hypothesis was supported by the observed elevated expression of GSDMD in individuals with SLE and further corroborated by the beneficial effects of GSDMD inhibitors in alleviating symptoms in lupus‐prone mice." (PMID 38881675, 2024). "Since activated GSDMD has a non-negligible role in mediating myeloid pyroptosis, we further analyzed the occurrence of pyroptosis under lupus induction." (PMID 38831451, 2024). "Earlier studies reported elevated GSDMD mRNA levels in PBMCs of SLE patients, along with enhanced expression of inflammasomes and GSDMD in macrophages and podocytes in the kidneys of lupus mice, and application of the GSDMD inhibitor disulfiram proved effective in treating lupus‐prone mice." (PMID 38881675, 2024). "IgG-depleted lupus serum failed to induce increased activation of caspase-1 and −11, along with the cleavage of GSDMD in neutrophils." (PMID 36797275, 2023). "On the one hand, consistent with our findings, expression and activation of GSDMD were increased in kidney specimens of SLE patients and lupus mice, which could be inhibited by combination therapy of different immunosuppressive agents." (PMID 36057687, 2022).
systemic lupus erythematosus (continued). "In this study, we aimed to determine whether GSDMD-mediated monocyte/macrophage pyroptosis promoted the development of SLE and DSF had a therapeutic effect on pristane-induced lupus (PIL) mice model." (PMID 36057687, 2022). "In systemic lupus erythematosus (SLE), FcγR activation downregulates SERPINB1 in neutrophils, leading to spontaneous activation of caspase-1/-11 and GSDMD cleavage." (PMID 39800780, 2025). "Unexpectedly, myeloid pyroptosis was not increased with elevated and activated GSDMD during LN, represented as the comparable percentages of caspase-1/11+PI+ cells or caspase-1/11+Hoechst+ cells gated on CD11b+ cells in the kidneys of lupus mice and their controls." (PMID 38831451, 2024). "The effect of DSF treatment in lupus model may not be solely attributed to GSDMD inhibition." (PMID 36797275, 2023). "Pioneering related work has revealed that global knockout of GSDMD exacerbated autoimmunity and renal inflammation in a TLR7 agonist-induced lupus model without elucidating the mechanism." (PMID 38831451, 2024). "Notably, elevated cleavages of Caspase 11 and GSDMD, markers of noncanonical pyroptosis, were detected in both J774A.1 and RAW264.7 cells after incubation with 20% lupus serum." (PMID 38881675, 2024).